ETS1 (ETS proto-oncogene 1, transcription factor)
Diseases named in the same sentence as ETS1 in open-access papers (continued):
Sharing a sentence is not in itself a finding about the gene and the disease.
bladder cancer (continued). "In order to evaluate the functional role of ETS-1 in human bladder cancer, vectors expressing ETS-1 shRNA and ETS-1 protein were constructed in vitro and transfected into the human bladder cancer T24 and 5637 cells." (PMID 27036016, 2016). "The relative expression level of ETS-1 was examined using real-time qPCR in a total of 42 patients with bladder cancer." (PMID 27036016, 2016). "More clinic samples should be needed to reveal the correlation of ETS-1 expression pattern with the clinical-pathological characteristics in bladder cancer." (PMID 27036016, 2016). "ETS-1 is likely to regulate the driven efficiency of artificial hTERT promoter in bladder cancer cells." (PMID 26743236, 2016). "As expected, ETS-1 promoted cell migration and cell invasion in the related bladder cancer cell lines." (PMID 27036016, 2016). "In conclusion, ETS-1 plays oncogenic roles through inducing cell migration and invasion in human bladder cancer, and it can be used as a therapeutic target for treating human bladder cancer." (PMID 27036016, 2016). "ETS-1 might regulate the transcriptional activity of artificial hTERT promoter in bladder cancer cells." (PMID 26743236, 2016). "Hence, ETS-1 should play oncogenic roles in human bladder cancer and it can be used as a therapeutic target for treating human bladder cancer." (PMID 27036016, 2016). "To further understand the biological functions of ETS-1 in bladder cancer, the ETS-1 specific shRNA and over-expression vector were designed to treat bladder cancer cells, and then we used scratch assay and invasion assay to detect the cell migration ability and the cell invasiveness." (PMID 27036016, 2016). "The elevated expression of GATA4 and ETS1 negatively correlated with the prognosis of bladder cancer patients and may be involved in bladder cancer relapse." (PMID 26625313, 2016). "Therefore, we aimed to study the expression pattern of ETS-1 and to determine its functional role in human bladder cancer." (PMID 27036016, 2016). "At 48 hours after transfection of ETS-1 shRNA or transduction of the over-expression vector, the relative activity of caspase-3 of the bladder cancer 5637 cells, T24 cells and UMUC-3 cells were detected by thecaspase-3 enzyme-linked immunosorbent assay (ELISA) assay." (PMID 27036016, 2016). "We demonstrated that the artificial hTERT promoter had a higher driven efficiency which might be regulated by transcription factor ETS-1 in bladder cancer cells, compared with wild-type hTERT promoter." (PMID 26743236, 2016). "Furthermore, the enhanced expression of GATA4 and ETS1 indeed contributed to the drug-resistance of bladder cancer cells." (PMID 26625313, 2016). "The results indicated that ETS-1 has nothing to do with the bladder cancer cell apoptosis." (PMID 27036016, 2016). "Specifically, the recurrent BCs and bladder cancer cells with MLL mutation displayed increased histone H3 tri-methyl K4 (H3K4me3) modification in tissue and cell levels and showed enhanced expression of GATA4 and ETS1 downstream." (PMID 26625313, 2016). "The future works are still needed to study the molecular mechanisms of ETS-1 which maybe a candidate biomarker for bladder cancer in the clinic." (PMID 27036016, 2016). "In addition, we found that ETS1 promotes PLA2G7 overexpression in bladder cancer cells." (PMID 40169540, 2025). "To verify whether the CRISPReader system can specifically recognize bladder cancer cells by sensing the expression of the transcription factor Ets-1, we transiently transferred the plasmid expressing the system into a series of cancer cells and corresponding normal cells." (PMID 34124154, 2021). "In this study, we introduced the MLL mutation into bladder cancer transitional cell line T24 and confirmed that the mutation didn't influence the expression of MLL but increased the H3K4me3 modification in GATA4 and ETS1 promoters and the expression levels of GATA4 and ETS1." (PMID 26625313, 2016).
bladder cancer (continued). "In addition, cell proliferation and cell apoptosis were tested by the CCK-8, EdU and ELISA assay to verify whether ETS-1 influences the cell proliferation and cell apoptosis in bladder cancer." (PMID 27036016, 2016). "However, the functional character of ETS-1 in human bladder cancer is still unclear." (PMID 27036016, 2016). "Further analysis of TCGA expression data revealed a significant positive correlation between ETS1 and PLA2G7 as well as PD-L1 expression in bladder cancer tissues." (PMID 40169540, 2025). "The mRNA expression levels of Ets-1 and MDR1 from 413 bladder cancer patients demonstrated positive correlation." (PMID 32131547, 2020). "In this paper, MLL particularly altered in recurrent bladder cancers with elevated modification of H3K4me3 and increased expression of GATA4 and ETS1 downstream." (PMID 26625313, 2016). "Therefore, to investigate whether the activity of the artificial hTERT promoter was also regulated by ETS-1, we co-transfected ETS-1 shRNA and the artificial hTERT promoter-driven reporter module into bladder cancer cells and tested the expression of the dual luciferase." (PMID 26743236, 2016). "Bladder cancer 5637, T24 and UMUC-3 cells were cultured and treated with ETS-1 shRNA or the over-expression vector." (PMID 27036016, 2016). "Finally, we determined whether ETS-1 inhibit cell apoptosis in bladder cancer." (PMID 27036016, 2016). "In summary, our study suggests that ETS1-mediated overexpression of PLA2G7 can regulate the phosphorylation of STAT1 and STAT3, leading to PD-L1 overexpression and promoting immune evasion in bladder cancer." (PMID 40169540, 2025). "Additionally, RASAL2 (RAS protein activator like 2) inhibited tumor angiogenesis via p-AKT/ETS1 (ETS proto-oncogene 1, transcription factor) signaling in bladder cancer." (PMID 33931059, 2021). "For instance, miR-199a-5p is known to inhibits VEGF-induced tumorigenesis and suppresses human bladder cancer cell metastasis by targeting C-C chemokine receptor type 7 (CCR7); this miRNA is also documented to target ETS-1 and suppresses HMEC angiogenesis by inhibiting VEGF and HGF signaling." (PMID 31188886, 2019). "Our results showed that the transcription factor ETS-1 could promote cell migration and cell invasion in human bladder cancer, without affecting cell proliferation and apoptosis." (PMID 27036016, 2016).
leukemia (15 papers, 2011 to 2025). A malignant (clonal) hematologic disorder, involving hematopoietic stem cells and characterized by the presence of primitive or atypical myeloid or lymphoid cells in the bone marrow and the blood. "Extending the concept would not only spread the use of PARPi over the wide range of carcinomas involving Ets-1 or Erg expression, but also over numerous leukaemias." (PMID 37686260, 2023). "In a subset of pediatric (3.7%) and adult (5.5%) T-ALL the LMO2 gene contains intronic indels that result in de novo binding sites for the leukemia-associated transcription factors MYB, ETS1 or RUNX1 and thus dysregulated LMO2 expression." (PMID 35514954, 2022). "In our study, we tested several dysregulated genes associated with leukemia by microarray data analysis, including MPL, GADD45g, TOB1, SLA, and ETS1, and mainly focused on MPL, which was reduced by PARP-1 inhibition." (PMID 26314963, 2015). "Reflecting their normal developmental roles in regulating proliferation and differentiation in a variety of tissues, misregulated activity of TEL1 and ETS1/2 provides an oncogenic driving force for a variety of solid tumors and leukemias." (PMID 22615925, 2012). "As in Drosophila, both TEL1 and ETS1/ETS2 operate as Ras pathway transcriptional effectors and misregulated activity of either factor has been implicated in many human leukemias and solid tumors." (PMID 22615925, 2012). "This analysis revealed M6 subtype of acute myeloid leukemia as a cancer type in which CIP2A and representative genes of each level of the pathway (EGFR, MEK2 and ETS1) were significantly upregulated in two different genome wide leukemia studies." (PMID 21445343, 2011). "Further investigation of this concept may facilitate the broader utilization of PARPi in other Ets‐1‐expressing carcinomas, and potentially even in Ets‐1‐expressing leukemias." (PMID 39778077, 2025). "Taken together, these findings indicate that INPP4B expression might be upregulated by NPM1-mA via ERK/Ets-1 signaling in leukemia cells." (PMID 29343273, 2018). "Quantitative promoter PCR was performed in selected, potential ERG targets genes related to PI3K or leukemia including AR, NUMB, NRG1, and ETS1 in AML A-E, and T-ALL ChIPs." (PMID 23300998, 2013). "Indeed, mice overexpressing NOTCH1 fail to develop leukemia when lacking functional ETS1 suggesting that both of these factors are required for leukemia initiation." (PMID 35514954, 2022).
pancreatic cancer (15 papers, 2011 to 2026). "ETS1 expression was detected in gemcitabine-resistant pancreatic cancer cells, and its silencing leads to the partial reversal of gemcitabine chemoresistance." (PMID 39685635, 2024). "At present, many studies have found that ETS1 expression is increased in colorectal, breast, prostate, gastric, and pancreatic cancers, and other malignant tumors 16, 35-38." (PMID 34659572, 2021). "Further investigations revealed that miR-181b is downregulated in radioresistant pancreatic cancer cell lines leading to the upregulation of the transcription factor ETS1 and the c-Met pathway." (PMID 33317198, 2020). "ETS-1 has been found to reduce cell migration and increase adhesion in pancreatic cancer cell lines by negatively correlating with E-cadherin expression." (PMID 29212244, 2017). "Our data showed that ETS-1 actively functioned as a regulator of EMT in Panc-1 cells, and provide additional evidence supporting a fundamental role for ETS-1 in metastatic pancreatic cancer cells." (PMID 25421630, 2015). "To elucidate the functionality of ETS-1 on EMT in pancreatic cancer cells, we constructed a green fluorescent protein (GFP)-expressing plasmid carrying ETS-1 short hairpin RNA (shRNA), and transfected Panc-1 cells with the plasmid." (PMID 25421630, 2015). "We probed the influence of ETS-1 silencing on the expression of the EMT-related molecules, E-cadherin, N-cadherin and VEGF, and we investigated the effects of transcription factor ETS-1 on the motility of Panc-1 pancreatic cancer cells." (PMID 25421630, 2015). "In the present study, we examined mRNA expression levels of ETS-1, E-cadherin and N-cadherin in five pancreatic cancer cell lines." (PMID 25421630, 2015). "We found that ETS-1 mRNA expression was positively correlated with N-cadherin and negatively correlated with E-cadherin mRNA expression in five pancreatic cancer cell lines." (PMID 25421630, 2015). "In conclusion, our data support that ETS-1 plays functionally significant roles in the metastasis of pancreatic cancer cells by regulating the expression of N-cadherin and E-cadherin involved in epithelial-mesenchymal transition." (PMID 25421630, 2015). "Later studies showed that Pim-3 is activated by the Ets-1 transcription factor in pancreatic cancer cells." (PMID 21646687, 2011). "ETS1 is known to have resistance to pancreatic cancer chemotherapy." (PMID 31739607, 2019). "Notably, ETS-1 is barely detectable in normal human pancreatic tissue, but high levels of expression are found in samples from human pancreatic cancer biopsies." (PMID 25421630, 2015). "Many cancers that overexpress cyclooxygenase-2 (COX-2) have been shown to have high intratumoral levels of PGE2, which has been shown to upregulate the invasive potential of pancreatic cancer cells through an ERK/Ets-1-dependent induction of MMP-2 expression and activity." (PMID 26135631, 2015). "Our data showed that ETS-1 functions as a regulator of EMT in pancreatic cancer cells, and suggest that analysis of ETS-1 expression levels may provide an avenue for evaluating prognosis in pancreatic cancer." (PMID 25421630, 2015). "We found that ETS-1 mRNA was expressed in four of five pancreatic cancer cell lines." (PMID 25421630, 2015). "Thus, there is compelling evidence showing that ETS-1 is involved in the migration and invasion of pancreatic cancer cells; however, the mechanisms by which ETS-1 mediates these effects have not been fully elucidated." (PMID 25421630, 2015). "Therefore, to determine whether ETS-1 silencing would reduce the motility of Panc-1 pancreatic cancer cells, we performed scratch and adhesion assays." (PMID 25421630, 2015). "By relieving the negative regulation of RREB1 on the ARHGEF2 promoter, we determined that ETS1 and SP3 are essential for the normal expression of ARHGEF2 and contribute to the migratory behavior of pancreatic cancer cells." (PMID 27835861, 2017).
pancreatic cancer (continued). "To evaluate the correlation between ETS-1 and EMT-related molecules, we analyzed the expression levels of ETS-1, N-cadherin and E-cadherin by RT-PCR in the following pancreatic cancer cell lines: PaTu-8988t, SW1990, Capan2, Panc-1 and BxPC3." (PMID 25421630, 2015). "Hence, by demonstrating a close relationship between ETS-1 and EMT-related molecules, we provide strong evidence that ETS-1 plays a crucial role in the process of EMT in pancreatic cancer cells." (PMID 25421630, 2015). "Although its mechanism remains incompletely understood, our results suggest the potential utility of ETS-1 as an adverse prognostic factor, and highlight the need for further research to elucidate the role and importance of ETS-1 during the progression of pancreatic cancer." (PMID 25421630, 2015). "However, the mechanisms of ETS1 involvement in the hypoxia-induced EMT process have not been fully elucidated in pancreatic cancer cells." (PMID 38057853, 2023). "However, the mechanisms of ETS-1 involvement in the EMT process have not been investigated in pancreatic cancer cells." (PMID 25421630, 2015). "Third, MACC1 is not the only regulator of MET, and there are many proteins other than MACC1 that can directly regulate MET expression (e.g., HIF1, SP1, AP1, and Ets-1), suggesting that MACC1 may not be a predominant regulator of MET in pancreatic cancer." (PMID 36333284, 2022). "However, the influence of ETS-1 on the expression of N-cadherin and E-cadherin involved in the EMT-derived phenotype has not been investigated in pancreatic cancer cells." (PMID 25421630, 2015).
rheumatoid arthritis (13 papers, 2014 to 2026). A chronic, systemic autoimmune disorder characterized by inflammation in the synovial membranes and articular surfaces. "Subsequently, many genetic studies reported that rs11221332 of ETS1 is associated with rheumatoid arthritis (RA) and celiac disease, both characterized by excessive activation of the immune system." (PMID 24708692, 2014). "Genetic variants in the human ETS1 gene have been associated with an increased risk of developing autoimmune and inflammatory disorders such as rheumatoid arthritis (RA), psoriasis, and ankylosing spondylitis." (PMID 41557627, 2026). "ETS1 gene variants are associated with susceptibility to various human inflammatory and autoimmune disorders in addition to several obesity-related conditions including rheumatoid arthritis (RA), systemic lupus erythematous (SLE), ankylosing spondylitis (AS), multiple sclerosis, and celiac disease." (PMID 29030598, 2017). "Because Ets1 has the capacity to coordinate Th17 cell differentiation, which is related to the rheumatoid arthritis (RA) onset." (PMID 40887825, 2025). "In this study, we aimed to identify whether polymorphisms of ETS-1 play a role in Rheumatoid arthritis (RA) susceptibility and development in Chinese Han population." (PMID 26241881, 2015). "Among the modules enriched for genes down-regulated with AD, M123, and its child module M444, anchored by ITK/IKZF3/ETS1, are significantly enriched for MS and rheumatoid arthritis etiologic genes, and, correspondingly, the modules are strongly enriched for a variety of immune functions." (PMID 38343831, 2024). "We hypothesized that ETS1 and WDFY4 polymorphisms may contribute to rheumatoid arthritis (RA) susceptibility." (PMID 24549174, 2014). "Recent research has provided evidence that ETS-1 might correlate with rheumatoid arthritis (RA), but it's not clearly defined." (PMID 26241881, 2015).
Autoimmunity (11 papers, 2017 to 2025). The occurrence of an immune reaction against the organism's own cells or tissues. "Our studies suggest that loss of IL-17 signaling can result in enhanced autoimmunity in Ets1 deficient autoimmune-prone mice." (PMID 37691956, 2023). "Ets1 deficiency in T cells has been linked to SLE-like autoimmunity in mice." (PMID 40979706, 2025). "For instance, Ets1 is known to regulate a number of basic biological processes in normal cells and has been linked to the regulation of immune cell function playing roles in immunity and autoimmunity." (PMID 37542675, 2023). "Ets1 is emerging as a key transcription factor that is required to prevent autoimmunity in mice and humans." (PMID 31356162, 2019). "Other autoimmunity‐related TFs, such as ETS‐1 and AIRE, were also upregulated." (PMID 28026094, 2017). "To determine if increased IL-17 production contributes to the development of autoimmunity in Ets1 KO mice, we crossed Ets1 KO mice to mice lacking the IL-17 receptor A subunit (IL17RA KO) to generate double knockout (DKO) mice." (PMID 37691956, 2023).
liver cancer (11 papers, 2013 to 2025). An epithelial or non-epithelial malignant neoplasm that arises from the liver. "WTAP has been shown to facilitate progression of liver cancer via m6A-HuR-dependent silencing of ETS1." (PMID 38169393, 2024). "The overexpression of WTAP in liver cancer contributes to the m6A modification of ETS1 mRNA, followed by apparent silencing of ETS1 in a HuR-related manner through the HuR-ETS1-p21/p27 axis, regulation of the G2/M phase, and increased progression." (PMID 34858499, 2021). "Our data is consistent with a publication showing Ets1 to be a target of miR-1 in a human liver cancer cell line." (PMID 23646287, 2013). "Although EFNA4 has been shown to promote metastasis in liver cancer, the contradictory mechanism of its high expression and good prognosis in GC remains to be elucidated, which may involve its antagonistic effects with ETS1, and requires further exploration." (PMID 41162582, 2025). "Conclusions: the persistent upregulation of c-Myc in the ATT-Myc liver cancer model, at both the gene and protein levels following DEN treatment inhibited the ETS1 transcription factor, further exacerbating the decline of c-Met signaling, SOD1, and NRF2." (PMID 40149719, 2025). "In liver cancer, WTAP was observed to increase the m6A level of the ETS1 mRNA, thereby facilitating cancer progression." (PMID 36207306, 2022). "Notably, shRNA-mediated knockdown of FOXA1 and FOXA2, along with sustained ETS1 expression, completely shifted HCC to intrahepatic cholangiocarcinoma development in primary liver cancer mouse models." (PMID 40149719, 2025). "In liver cancer, WTAP suppressed ETS1 expression via m6A-HuR-dependent epigenetic silencing." (PMID 33748145, 2021).